TGFB1 (transforming growth factor beta 1)
Diseases named in the same sentence as TGFB1 in open-access papers (continued):
Sharing a sentence is not in itself a finding about the gene and the disease.
pulmonary fibrosis (continued). "In rodent models of lung fibrosis, mice exposed to BLM displayed increased expression of TNFα that was associated with TGFβ levels; moreover, adenoviral mediated TNFα overexpression in otherwise normal rat lungs resulted in upregulation of TGFβ1 and accumulation of αSMA expressing myofibroblasts." (PMID 37849737, 2023). "On the other hand, in a pulmonary fibrosis rat model induced by intra-tracheal injection of bleomycin, it was observed that prodigiosin attenuates pulmonary fibrosis by inhibiting miR-410 and leading to the downregulation of the TGFβ1/ADAMTS-1 signaling pathway." (PMID 35743055, 2022). "C/EBPβ also plays an important role in experimental lung fibrosis, as demonstrated by C/EBPβ null mice that developed less lung fibrosis after bleomycin injury due to the reduced production of lung pro-inflammatory cytokines TGFβ1, TNF-α, and IL-1β, and myofibroblast differentiation." (PMID 34207528, 2021). "Nrf2 induced by bixin could suppress the TGFβ1 signaling in lung fibrosis." (PMID 33313043, 2020). "In addition, TGFβ1 may promote exacerbation of pulmonary fibrosis by directly suppressing both the innate and adaptive immune systems leading to enhanced host susceptibility to infection." (PMID 32210242, 2020). "Key pro-fibrotic cytokines and chemokines were also upregulated including CCL11 (eotaxin); CCL11−/− deficient mice have reduced bleomycin-induced pulmonary fibrosis and expression of pro-fibrotic cytokines such as TGFβ1 are diminished in the absence of CCL1137." (PMID 29321510, 2018). "Hence, we hypothesized that Nogo-b/MMP14 signaling pathway was affecting the process of pulmonary fibrosis by influencing the TGFβ1 signaling pathway." (PMID 29050340, 2017). "In a bleomycin (BLM)-induced pulmonary fibrosis model, miR-497-5p was upregulated, and suppressing miR-497-5p expression using a lentiviral agent in vivo reduced the expression of fibrotic markers Mmp2, Mmp9 and Tgfb1 via enhancing the expression of Reck, suggesting augmented in vivo lung repair." (PMID 28098218, 2017). "Smad3 may be a central TGFβ1 signalling intermediate in the pathogenesis of pulmonary fibrosis." (PMID 27494713, 2016). "Therefore, USP11 may contribute to the pathogenesis of pulmonary fibrosis by stabilization of TβRII and promotion of TGFβ-1 signaling." (PMID 27853171, 2016). "Interestingly, bleomycin treatment leads to lung fibrosis due to increased activation of TGFβ1." (PMID 23547562, 2013). "Importantly, knockdown of the TGFβ1/Smad3 signaling pathway inhibits experimental lung fibrosis." (PMID 22997505, 2012). "Because phosphorylation of Smad signaling by the activated TGFβ1 receptor I is a major step in the initiation of TGFβ1 signal transduction, we further examined whether Smad2 and Smad3 phosphorylation in bleomycin-induced pulmonary fibrosis was changed by AG treatment." (PMID 19552800, 2009). "Moreover, TGFβ, especially the isoform TGFβ1, is a key fibrotic stimulator in pulmonary fibrosis." (PMID 19552800, 2009). "After treatment with d-limonene at 25–100 mg/kg, rats with lung fibrosis exhibited reduced levels of hydroxyproline (HYP) in lung tissue and decreased serum expression of transforming growth factor beta-1 (TGF-β1) compared to the control group." (PMID 40429833, 2025). "Moreover, previous reports have indicated that TSG effectively mitigates pulmonary fibrosis through modulation of TGFβ1 signaling pathways and reduction of ROS, which may also contribute to its beneficial effects in asthma by reducing airway inflammation and remodeling." (PMID 40598285, 2025). "Mangiferin (MANG) and gentiopicroside (GENPD) have been shown to have an anti-fibrotic effect in preclinical studies for treating pulmonary fibrosis by regulating inflammatory markers (TNF, IL-17, and IL-6) and TGFβ1/Smad and TNF-α/NF-κB signalings." (PMID 41361355, 2025).
pulmonary fibrosis (continued). "The study has shown that TMEM176B can inhibit the TGFβ1-SMAD signaling pathway, which is critical for fibroblast proliferation, differentiation, and extracellular matrix production - key features of pulmonary fibrosis." (PMID 39170226, 2024). "Transforming Growth Factor Beta 1 (TGF-β1) plays a critical role in the development and progression of pulmonary fibrosis." (PMID 39512901, 2024). "Upregulated TXNDC5 can enhance TGFβ1 signaling by promoting the folding and stabilization of TGFBR1 in lung, leads to pulmonary fibrosis (PF)." (PMID 38629066, 2024). "Nevertheless, the current study demonstrates the molecular interactions between TGFβ1 and the SEMA3B-NRP1 axis in altering the expression of ECM production and pulmonary fibrosis." (PMID 38646784, 2024). "Secreted factors such as transforming growth factor β1 (TGFB1) and connective tissue growth factor (CTGF, also known as CCN2) are the notorious pro-fibrotic agents involved in the initiation and progression of pulmonary fibrosis." (PMID 38900131, 2024). "In our study, the downregulation of the expression levels of Tgfb1 and Tgfb2 in the lungs was demonstrated, suggesting a central mechanism to ameliorate BLM‐induced pulmonary fibrosis." (PMID 36949656, 2023). "Transforming growth factor-β1 (TGFβ1) is a multifunctional cytokine that is a well-known mediator of FMT and a major player in the development and progression of pulmonary fibrosis." (PMID 36767821, 2023). "GRK2 promoted TGFβ1-induced ECM accumulation by transcriptionally activating Smad3 in lung fibroblasts, the inhibition of which thus attenuated bleomycin-induced lung fibrosis." (PMID 37815883, 2023). "Both transforming growth factor beta 1 (TGFβ1) and fibronectin 1 (FN1) are known to be drivers of pulmonary fibrosis." (PMID 35288537, 2022). "In the present study, we further investigated the anti-pulmonary fibrosis and mechanism of DME targeting lncIAPF–HuR complex in TGFβ1-stimulated lung fibroblast and bleomycin (BLM)-treated mice." (PMID 36386240, 2022). "Mannosylated albumin nanoparticles incorporating TGFβ1 small-interfering RNA (siRNA) targeted the profibrotic subpopulation of CD206+ macrophages and prevented lung fibrosis." (PMID 35377803, 2022). "In radiation-induced pulmonary fibrosis, the interaction of Foxm1 and Snail1 activates TGFβ1-induced EMT and promotes pulmonary fibrosis." (PMID 33639908, 2021). "EGR1 is a candidate transcription factor in this pathway because it has been reported downstream of TGFβ1 signaling in human dermal fibroblasts, and the EGR1-TGFβ1 relationship is important in a murine model of pulmonary fibrosis." (PMID 33640015, 2021). "In a study on pulmonary fibrosis, ITGB6 was found to be the key activator of TGFβ1 in lung epithelial cells." (PMID 34621667, 2021). "In this study, we observed the lung injury, collagen content, and TGFβ1/NOX4 and PDGF/ROCK signal pathway of pulmonary fibrosis rats after the administration of Yifei decoction combined with MitoQ." (PMID 34135982, 2021). "In this experiment, we confirmed that the expression of TGFβ1, NOX4, PDGF, and ROCK increased significantly in the rat model of pulmonary fibrosis." (PMID 34135982, 2021). "Among the numerous genes whose expression is regulated by TGFβ1 and HIF1α, PAI-1 has been shown to play a key role in pulmonary fibrosis development." (PMID 33805152, 2021). "Transforming growth factor-beta 1 (TGF-β1), a fibrogenic cytokine, can stimulate EMT in pulmonary fibrosis." (PMID 34681813, 2021). "After treatment with Yifei decoction combined with MitoQ, the signal of TGFβ1/NOX4 and PDGF/ROCK and the development of pulmonary fibrosis were inhibited." (PMID 34135982, 2021). "A former study proved that Feibi Recipe can effectively inhibit the overexpression of IL-6/TGFβ1/P38MAPK cell signaling pathway and reduce pulmonary fibrosis of the bleomycin model rat." (PMID 33101446, 2020).
pulmonary fibrosis (continued). "Idiopathic pulmonary fibrosis (IPF), the most common interstitial lung disease, arises from transforming growth factor beta 1- (TGFβ1-) induced aberrant fibroproliferation in response to epithelial injury." (PMID 32258117, 2020). "Then, we determined the effect of LEPLCs on the expression of extracellular matrix components involved in the progression of lung fibrosis, including collagen types I and III, and transforming growth factor-beta 1 (Tgf-β1)." (PMID 31196196, 2019). "DHP mainly regulated pulmonary fibrosis-related inflammatory genes and signaling pathways, such as IL1β, IL4, IL5, IL6, TGFβ1, and TNFα." (PMID 31105564, 2019). "In this study, bleomycin-induced pulmonary fibrosis was characterized by increases in CTGF, TGFβ1, ET-1, IL-6, and IL-13, as profibrotic mediators." (PMID 29409529, 2018). "TGFβ mediates epithelial-to-mesenchymal transition (EMT), and reduction of TGFβ1 levels in a mouse model of pulmonary fibrosis blunted fibrosis." (PMID 29168738, 2017). "Like TGFβ1, IGF1 is elevated in the lungs of patients with IPF as well as in animal models of pulmonary fibrosis." (PMID 26059457, 2015). "Iloprost prevents bleomycin-induced pulmonary fibrosis, possibly by upregulating antifibrotic mediators (IFNγ and CXCL10) and downregulating pro-inflammatory and pro-fibrotic cytokines (TNFα, IL-6, and TGFβ1)." (PMID 20302663, 2010). "Further, AG treatment also decreased BLM-induced HSP47 expression, downregulated TGFβ1, p-Smad2 and p-Smad3 expressions, and subsequently attenuated BLM-induced pulmonary fibrosis." (PMID 19552800, 2009). "Overexpression of miR-320a-3p has been shown to suppress TGFβ-1-induced EMT in alveolar epithelial cells, preventing their conversion into mesenchymal cells and reducing collagen deposition, lung tissue destruction, and pulmonary fibrosis." (PMID 40332537, 2025). "In pulmonary fibrosis, NAT10 accelerates disease progression by stabilizing transforming growth factor beta 1 (TGFB1) mRNA in an ac4C-dependent manner, promoting epithelial-to-mesenchymal transition (EMT) and fibrosis upon exposure to ambient particulate matter." (PMID 40588654, 2025). "In the rat study investigating the effects of Ole on pulmonary fibrosis induced by intratracheal bleomycin, TNF-α, IL-13, TGFβ1, Platelet-derived growth factor (PDFG), lung collagen index and MDA increased significantly in BALF, but Ole prevented pulmonary fibrosis by reversing these effects." (PMID 40233022, 2025). "Further, the nuclear localization of miR-9 was confirmed by RNA fluorescence in situ hybridization (FISH) in MLg cells and hLF from control donors (Ctrl hLF) or patients with idiopathic pulmonary fibrosis (IPF hLF), a lethal interstitial lung disease involving TGFB1 signaling." (PMID 39706840, 2024). "One of the major downstream effects of the TGFβ1-SMAD signaling pathway includes the regulation of fibroblast proliferation and differentiation into myofibroblasts, a key event in the development and progression of pulmonary fibrosis." (PMID 39170226, 2024). "NRPs interact with SEMAs and other growth factors, including vascular endothelial growth factor (VEGF), TGFβ1, fibroblast growth factors, and platelet-derived growth factor-BB (PDGF); these growth factors are also known to participate in the development of pulmonary fibrosis." (PMID 38646784, 2024). "Viral induction of TGFB1 predicts profibrotic signaling to most epithelial cells and fibroblasts expressing both TGFBR1 and TGFBR2, including myofibroblasts, which constitute the fibroblast foci in lung fibrosis." (PMID 38597954, 2024). "This anti-pulmonary fibrosis of intratracheal iPSCs-conditioned medium was subsequently reported to be partially mediated by hepatocyte growth factor (HGF), accompanied by reduction of the collagen deposition, TGFβ1, and α-SMA expression in rat lungs." (PMID 38886859, 2024).
pulmonary fibrosis (continued). "In addition, a member of class III histone deacetylase, SIRT1, was shown to be elevated in a bleomycin-induced lung fibrosis murine model, IPF patients, and human primary lung cell lines (MRC-5) treated with TGFβ1." (PMID 37569677, 2023). "Moreover, the beneficial effect of GB is abolished after incubated with pirfenidone (PFD, a drug for idiopathic pulmonary fibrosis, IPF), which can inhibit Tgfβ1." (PMID 38125702, 2023). "It has been reported that lung fibrosis is mediated by TGFβ1 signaling rather than the expression of TGFβ1 in both epithelial and fibroblastic cells." (PMID 38132468, 2023). "MiR-627 attenuates TGFβ1-induced proliferation of normal human primary lung fibroblasts by downregulating HMGB1 and inhibiting the NF-κB pathway, thereby alleviating the development of pulmonary fibrosis." (PMID 36163195, 2022). "To interrogate this hypothesis, we evaluated the relationship between the levels of corisin and fibrosis markers in TGFβ1 TG and BLM-induced mouse models of pulmonary fibrosis." (PMID 35322016, 2022). "TGFB1 suppresses GCL expression and increases lipid peroxidation in mouse lungs, indicating that ferroptosis may be involved in pulmonary fibrosis." (PMID 33268902, 2021). "lncAP003419.16 is highly expressed in TGFβ1‐treated alveolar epithelial cells and IPF patients, in which lncAP003419.16 facilitates pulmonary fibrosis via the mammalian target of rapamycin (mTOR) signaling pathway dependent on its adjacent gene ribosomal protein S6 kinase B‐2 (RPS6KB2)." (PMID 33533071, 2021). "TGFB1 signaling and EMT are both playing a crucial role in idiopathic pulmonary fibrosis (IPF)." (PMID 33594057, 2021). "Collectively, TGFβ1 can induce both canonical and non-canonical signaling to promote alveolar epithelial cell apoptosis and lung fibrosis." (PMID 34209019, 2021). "It participates in the neural signal transduction related to pulmonary fibrosis, including MAPK neural signal transduction pathway, PKC neural signal transduction pathway, TGFβ1/Smad neural signal transduction pathway, and JAK-STAT neural signal transduction pathway." (PMID 34135982, 2021). "Interestingly, TGFβ1 induced UPR markers only in IPF lung fibroblasts, suggesting a greater-than-anticipated role of ER stress and UPR signaling in lung fibrosis." (PMID 34209019, 2021). "Therefore, the TGFβ1/NOX4 and PDGF/ROCK pathways regulate each other in the process of pulmonary fibrosis." (PMID 34135982, 2021). "We separated lung immune cells from each WT mice without fibrosis, TGFβ1 TG mice without lung fibrosis and TGFβ1 TG mice with fibrosis and compared the percentage of cells between groups." (PMID 32210242, 2020). "SARS-CoV-2 infection increased ACE2, TGFB1, CTGF and FN1 mRNA that were drivers of lung fibrosis." (PMID 32664949, 2020). "We found significantly enhanced level of corisin in TGFβ1 TG mice with lung fibrosis compared to WT mice and TGFβ1 TG mice without fibrosis." (PMID 32210242, 2020). "There was a significant increase in the percentage of monocyte/macrophages and regulatory (CD4+CD25+) T cells in TGFβ1 TG mice with lung fibrosis compared to WT and TGFβ1 TG mice without lung fibrosis." (PMID 32210242, 2020). "There was significantly higher concentration of Na+ in lung tissue from TGFβ1 TG mice with lung fibrosis compared to TG mice without lung fibrosis and WT mice." (PMID 32210242, 2020). "The percentage of total T cells was not different between groups, but the percentage of B cells was significantly decreased in TGFβ1 TG mice with lung fibrosis compared to WT and TGFβ1 TG mice without lung fibrosis." (PMID 32210242, 2020). "In addition, CD44v6 and CD44v10 splice variants were significantly higher in AD hippocampal neurons, and in lung fibrosis, CD44v6 is mediating the induction of COL1 pro-fibrotic action of TGFβ1." (PMID 29706885, 2018).
pulmonary fibrosis (continued). "We demonstrate that mEVs, but not fibroblast EVs (fEVs), suppress TGFβ1-induced myofibroblastic differentiation of normal and idiopathic pulmonary fibrosis (IPF) lung fibroblasts." (PMID 29273797, 2017). "As USP11 promotes TGFβ-1 signaling through stabilization of TβRII, we hypothesize that USP11 may have a critical role in the development of lung fibrosis." (PMID 27853171, 2016). "In addition, IL-27 potentially inhibits the pulmonary fibrosis by regulating T cell differentiation and the secretion of IL-17 and other cytokines and suppressing the JAK/STAT and TGFβ1/SMAD signaling pathways." (PMID 25888222, 2015). "Furthermore, we found that TGFβ1 represses autophagy, mitochondrial recycling, and homeostasis in normal human lung fibroblasts during FMD and inhibits PINK1 expression during pulmonary fibrosis." (PMID 26059457, 2015). "In addition to TGFβ1, FIZZ1 is recently identified as another inducer of myofibroblast differentiation in pulmonary fibrosis." (PMID 24516640, 2014). "Transforming growth factor beta 1 (TGF-β1) is a pro-fibrotic cytokine which is increased in several forms of acute and chronic adult lung diseases such as asthma, COPD, and pulmonary fibrosis." (PMID 23762390, 2013). "TGFβ1 mRNA expression in alveolar macrophages from lung tissue from patients with idiopathic pulmonary fibrosis is abundant in sites of active fibrosis but not in the lung parenchyma of a patient with primary pulmonary hypertension." (PMID 24286074, 2013). "Although TGFβ1 is a critical initial key response factor after injury, it must be recognised that in humans other cytokines including CTGF, collagen and angiogenic mediators are involved in the pathogenesis of pulmonary fibrosis." (PMID 17883846, 2007). "In the context of lung fibrosis, for example, investigating the role of ITGB1 and TGFβ-1 in the development of VILI and acute respiratory distress syndrome (ARDS) could provide valuable insights into how mechanical stress leads to fibrotic changes in lung tissue." (PMID 41154695, 2025). "In addition, the study showed that the treatment with nintedanib of cultured M2 macrophages significantly reduced the release of the active form of TGFβ1 growth factor, that is overexpressed in SSc patients with ILD and potentially involved in the development of lung fibrosis." (PMID 38509595, 2024). "Therefore, in this study we sought to define whether platelets, and more specifically, platelet-derived TGFβ1, mediate IPF disease progression using both clinical patient samples and an animal model of pulmonary fibrosis." (PMID 37643008, 2023). "Therefore, DPP4 deficiency in those cell types might relate to the low expression levels of Tgfb1 and Tgfb2 in the lungs with BLM‐induced pulmonary fibrosis." (PMID 36949656, 2023). "To this end, we intratracheally administered Staphylococcus nepalensis strain CNDG, which contains the corisin sequence, or Staphylococcus epidermidis [ATCC14990], as negative control, to germ-free TGFβ1 TG mice separated in three groups with matched lung fibrosis CT scores." (PMID 32210242, 2020). "HSP90α is able to promote the phosphorylation of Protein kinase B (AKT) in Thr308, P38, and extracellular signal–regulated kinase (ERK) signaling pathways, which are known downstream non-Smad-pathways of TGFβ1 signaling and participate in the development of pulmonary fibrosis." (PMID 32722485, 2020). "Previous studies have also reported that HFD induces peribronchial and perivascular collagen deposition via activation of the transforming growth factor‐beta‐1 (TGF‐β1) signalling pathway, thereby inducing pulmonary fibrosis regardless of whether mice were exposed to allergens." (PMID 37345264, 2023). "Together these findings demonstrate that whilst TGFβ1 has a dominant role in increasing the rate of synthesis of major fibrillar collagens, HIF pathways may have a key role in regulating pathological post-translational modifications and collagen structure in lung fibrosis." (PMID 35188460, 2022).